IL6 (interleukin 6)
Diseases named in the same sentence as IL6 in open-access papers (continued):
Sharing a sentence is not in itself a finding about the gene and the disease.
infection (continued). "The data demonstrate that IL-6 is significantly upregulated during infections with different IAV strains, including H5N1 and H7N9, contributing to proinflammatory responses, viral clearance, and tissue protection." (PMID 40692679, 2025). "Although CRP is a classical acute-phase reactant synthesized in hepatocytes via IL-6, it is elevated not only in infections but also in malignancies, autoimmune diseases, and trauma." (PMID 40941711, 2025). "H. Pylori-infected C57BL/6 mice also developed SPEM 6 months after infection, accompanied by increased expression of IL-6, p-STAT3, and the proliferative marker Ki6711,40." (PMID 40520011, 2025). "IFN-γ: activates macrophages; induces IL-6, TNF-α, IL-10 production via JAK-STAT; IFNγR1 deficiency increases infection susceptibility." (PMID 41268545, 2025). "While the organ-on-chip recapitulated the GRO-α, MIP-1α, and IL-6 responses to infection with the capsular serotype III strain (GB112) in the human choriodecidual punch biopsy samples, other inflammatory mediators had differential expression." (PMID 41277827, 2025). "To assess infection-driven inflammation, we analyzed the levels of IL-6 and IFNγ cytokines, which are involved in inflammation and immune activation, and the chemokines IP-10, MCP-1, and MIP-1β, which are primarily involved in the recruitment of immune cells." (PMID 40272151, 2025). "The NLRP6‐DHX15 protein complex was further found to be essential for the release of IFN‐β, IFN‐λ3, IL‐6, and IL‐18 through MAVs in human intestinal epithelial cells upon stimulation with polyI:C and infection with various RNA viruses." (PMID 39878363, 2025). "Rapid production of IL-6 contributes to host defense during infection and tissue injury, but excessive IL-6 synthesis is involved in PTB pathology." (PMID 40538732, 2025). "TIL-produced CFS at 5% effectively reduced IL-6 after infection (p < 0.001), with a greater effect when vitamin D was added (p < 0.0001), which reduced IL-6 levels even when compared to the mock (p < 0.0001)." (PMID 40351306, 2025). "When tissue damage or inflammation due to infections or injuries occurs, IL-6 synthesis is promptly induced, peaking 2–6 h afterwards." (PMID 41302151, 2025). "By contrast, in elderly patients, G-CSF responses were blunted, together with IL-6 and MCP-1, a pattern associated with impaired neutrophil mobilization and increased infection risk." (PMID 41155423, 2025). "For the lung tissue explants, influenza H5N1 virus infection significantly induced the mRNA expression of ISG15, MCP-1, and MDA-5 and trends in the upregulation of IFN-α, IP-10, and IL-6 were also observed when compared with mock infections." (PMID 40431161, 2025). "In the case of MHV-JHM infection, changes in expression (from 0% to 100%) were visible in IL-6, IL-18, IL-33, ENA-78 (CXCL5), GRO alpha (CXCL1), IP-10 (CXCL10), MCP-1 (CCL2), MIP-1 beta (CCL4), MIP-2 alpha (CXCL2), RANTES (CCL5), and TNF alpha." (PMID 40358160, 2025). "The levels of IL-6 positively correlate with the severity of infection and inflammation, and it plays a pivotal role in the pathogenic process of pneumonia infections." (PMID 40022245, 2025). "Although this study provides valuable insights into the utility of Presepsin and IL-6 as early biomarkers for infection in HTx patients, further research is needed to validate these findings in larger patient cohorts." (PMID 40806991, 2025). "The ΔretS infection increased cell death, inflammatory factors (IL-1β, IL-6, TNF-α), and reactive oxygen species compared to a T6SS-inactive strain." (PMID 40557319, 2025). "Similar results were seen for TIL-L3 CFS (p < 0.05 for 10%, p < 0.01 for 5% vs. the infected control), with vitamin D significantly increasing the 5% L3 CFS ability in reducing IL-6 levels upon infection (p < 0.0001)." (PMID 40351306, 2025).
infection (continued). "During infections involving iron-dependent pathogens, inflammatory cytokines such as IL-6 are generated as part of the innate immune response, a process primarily mediated by macrophages, which release IL-6 in response to infection/inflammation." (PMID 41007630, 2025). "The mRNA abundance of TNF-α, IL-1β and IL-6 were significantly up-regulated from 6 h to 24 h post infection, while those of iNOS, Arg-1 and IL-10 did not change significantly from 18 h to 24 h post infection." (PMID 40663568, 2025). "Both mouse strains exhibited low levels of IL-6 and IL-10 following infection with the icmQ::Tn mutant, which is consistent with the rapid clearance of this mutant by the immune system." (PMID 40586810, 2025). "Interleukin-6 (IL-6), a pleiotropic cytokine, is induced by infection of influenza A virus (IAV), where it plays a pivotal role in immune defense and the regulation of inflammation." (PMID 40692679, 2025). "IL‐6 rises sharply in the early stages of infection, promotes T cell activation and proliferation, B cell differentiation, and induces the production of autoantibodies." (PMID 40757669, 2025). "Generally, IL-6 is a cytokine elevated during the acute phase of infection acting as a strong activator of the inflammatory response and is also an adipokine (cytokine secreted by adipose tissue) that will induce lipolysis." (PMID 40586810, 2025). "This increase is likely related to infection and inflammation, as the body releases large amounts of inflammatory mediators such as IL-6, which stimulate bone marrow platelet production." (PMID 40012747, 2025). "For instance, IL-6 was shown to be crucial for resolving infection by protecting neutrophils from virus-induced death and enhancing their viral clearance activity." (PMID 40692679, 2025). "Similarly, host genetic factors, such as polymorphisms in the IL-6 gene promoter region (e.g., -174G/C), are known to affect cytokine responses to infection and may predispose specific populations, including those of South Asian descent, to more severe cytokine storms." (PMID 40959673, 2025). "PCT provides an infection-specific signal, while IL-6 reflects systemic inflammatory burden; their ratio is expected to reduce inter-individual variability and address limitations inherent to each marker when used alone." (PMID 41347097, 2025). "While IL-6 < 10 pg/mL achieved an NPV of 82% for excluding severe infection, higher thresholds (>100 pg/mL) performed poorly (sensitivity 36%, specificity 24%, PPV 11%)." (PMID 40647525, 2025). "Functionally, these molecular alterations translated into a diminished secretion of key inflammation and infection mediators, such as interleukin-6 (IL-6) and C-C Motif chemokine ligand 5 (CCL5) upon TNF-a stimulation." (PMID 41050669, 2025). "Pathogen infection or viral proteins induce the release of inflammatory cytokines such as IL-6 and TNF-α, which subsequently suppress key antioxidant proteins like GPX4 and SLC7A11, initiating ferroptosis." (PMID 41479924, 2025). "Mean concentration values [pg/mL] ± standard deviation of selected proinflammatory cytokines: TNF-alpha, IL-1β and IL-6 in infections with atypical pathogens in patients with PCOS." (PMID 40647668, 2025). "Infection induces a pro-inflammatory environment characterized by cytokine release (e.g., IL-6, TNF-α), which recruits immune cells but also contributes to endothelial dysfunction by increasing permeability and causing vascular damage." (PMID 40141288, 2025). "Some treatments not only mitigated the infection-induced rise of the early inflammatory marker IL-6, which is crucial to restore eubiosis and modulate immunity, but also reduced its levels below those of untreated cells." (PMID 40351306, 2025). "Infection with P. aeruginosa can not only increase the levels of the proinflammatory cytokines IL-1β, IL-6, and TNF-α but also reduce the expression of the inhibitory cytokine IL-10." (PMID 40270824, 2025).
infection (continued). "In subtype C, we found that the changes in the biomarker profiles post infection compared to pre-infection were due to increases in TNFα, IL-10, IL-6, IL-13, IL-5, IFNγ, IL-12, IL-4, ITAC, IL-17α, and IL-23." (PMID 40862133, 2025). "In humans, the transcription factor p65 is a central transcriptional activator of pro-inflammatory cytokines, including TNF-α, IL-1β, and IL-6, playing pivotal roles in the response to infection, immune cell activation, and inflammatory resolution." (PMID 41141596, 2025). "The secretion of IL-6 acts as a signal for other microglia and astrocytes to migrate to the site of infection, creating an additive production of inflammatory cytokines and potential neurotoxins." (PMID 40584180, 2025). "IL-1β regulates spermatogenesis and IL-6 is cytokines produced in response to infection and tissue damage." (PMID 38629098, 2024). "In previous studies, HP-PRRSV BB0907 strain infection increased IL-1β, IL-6, TNF-α, and IFN-γ levels in the serum, and infection with the highly pathogenic PRRSV-1 Lena strain increased the serum levels of IFN-γ and IL-6." (PMID 39506759, 2024). "IL-6, the prototypical member of the family, is expressed by different cell types, such as immune cells, endothelial cells, and fibroblasts, during infection, tissue damage, or inflammation." (PMID 38251210, 2024). "The increase of infection related indexes, for example, serum levels of IL-1β, TNF-α, and IL-6, were significantly associated with a blood glucose rise." (PMID 38570745, 2024). "Inflammatory cytokines such as tumor necrosis factor-alpha (TNF-α), and interleukin-6 (IL-6) act as potent chemoattractant, effectively facilitating the recruitment and mobilization of immune cells towards the precise location of infection." (PMID 38997643, 2024). "In order to define the time course of gene expression for IL-1β and IL-6, RNA analysis was performed at 24 h, 48 h and one week after infection with the highest bacterial concentration." (PMID 38399810, 2024). "The inflammatory response, often activated as a result of infection, injury, or stress, leads to the release of pro-inflammatory cytokines, such as interleukin-6, tumor necrosis factor-alpha, and interleukin-1 beta." (PMID 39355377, 2024). "As illustrated with our results, the levels of IL-6, IL-8 and IL-1β gradually increased with the duration of CV-A10 infection." (PMID 38641810, 2024). "After 24 h of infection, both T. forsythia stimuli significantly upregulated gene expression of IL-6, TNF-α, IL-8, and MCP-1." (PMID 39035711, 2024). "Consistently, we observed significantly higher IL-6 levels in primary Mettl3 cKO BMDM compared to Mettl3 WT BMDM following infection with P. multocida and S. aureus for 0–12 h, and M. pneumoniae for 0–24 h, as well as TNF-α." (PMID 38182816, 2024). "Patients with IL-6 levels lower than 84.00 pg/mL on POD 3 can ensure safe early discharge with a low probability of infection." (PMID 38504206, 2024). "Both mouse strains have higher levels of TNFα, IL-6, IL-17A, and IL-17F in whole stomach homogenates after infection, illustrating that the type 3 model of gastric mucosal inflammation and C. albicans pathogenesis is applicable in both C57BL/6 and BALB/c mice." (PMID 39347572, 2024). "Within 72 h of anti‐infection, the predictive ability of serum IL‐6 and CRP increases with the prolongation of antibiotic time." (PMID 38967137, 2024). "Pro-inflammatory cytokines (IL-1 and IL-6) are released in response to tissue injury, inflammation, and infection." (PMID 39682700, 2024). "Treatment with a ROS scavenger (N-acetyl cysteine, NAC) before infection with S. uberis reduced antioxidative responses and the inflammatory response, including the cytokines IL-6 and TNF-α, and the formation of the Atg5-LC3II/LC3I autophagosome." (PMID 38397769, 2024). "Our experiments indicated that MDA-MB-468 cells produced more IL-6 after rMeV-Hu191 infection compared to MDA-MB-231 cells." (PMID 39342391, 2024).
infection (continued). "The anti-PySRA-F2 antibody can protect mice against P. yoelii, and the pro-inflammatory responses such as IL-1β, TNF-α, and IL-6 after infection with P. yoelii are attenuated." (PMID 38624215, 2024). "Contrarily, has-miR-155 mimics repressed the KRAS expression and ERK1/2 activity in hBMECs upon infection, subsequently attenuating the expression of IL-6, MIP-2, and E-selectin." (PMID 38360663, 2024). "Analysis of mice lacking the major cytokines produced in response to the virus showed that HSC activation is dependent on IL-1β in the early phase and IL-6 in the later phase of infection." (PMID 39720722, 2024). "Following infection with T. gondii, proinflammatory cytokines, including interleukin (IL)‐1, IL‐6, IL‐12, and tumor necrosis factor, as well as IL‐17, have been reported to be involved in the development of immune responses." (PMID 38270309, 2024). "Compared with WT infection, deletion of yfiD led to the superior transcription of IL-1α (NP_034684.2), IL-1β (NP_032387), and IL-6 (NP_112445.1)." (PMID 38332126, 2024). "Meanwhile, Hcrt-1 regulates infection-induced inflammation by modulating the IL-6 and TNF-α in microglia and has a protective role against ischemia stress." (PMID 39839304, 2024). "The levels of pro-inflammatory cytokines such as IL-1α, IL-1β, IL-2, IL-6, IL-12, IL-17, INFγ, and TNFα increased in the serum of mice infected with fungal strains from a very early stage (3 h) to 7 days post infection." (PMID 38783167, 2024). "Our study shows BRD infection increases the potential of the immune cells to produce IL-6, at early stage of infection, in advance of hematological changes and the development of pathology." (PMID 39541407, 2024). "In an in vitro infection model with T. gondii, pre-treatment of macrophages with IL-6 has been observed to result in increased parasite multiplication within the parasitophagous vacuoles." (PMID 38455048, 2024). "K-RasLA1 and wild-type mice were infected with 40,000 pfu of MHV68 or mock-infected and harvested 7 days post-infection, a time of peak expression of Il-6, Csf3, and Cxcl1 mRNAs." (PMID 39338937, 2024). "Nitric oxide (NO) and other inflammatory mediators, including IL-6 and -CSF, are produced by highly activated macrophages as a result of the infection." (PMID 38390861, 2024). "Cells were transfected with Raptor or Rictor siRNA along with control siRNA 48 h prior to infection with R. rickettsii (SS); RNA was then isolated, and expression levels of IL-6, IL-8, and IL-1α were determined using their respective primer pairs." (PMID 38399700, 2024). "A growing number of studies correlate the levels of type 1 proinflammatory cytokines (IFN-γ, TNF-α), IL-6 and IL-8 post-infection with enhanced disease burden and poor patient outcome, which was in line with the finding in our research." (PMID 38933114, 2024). "While IL-6 decreases quickly in the first 12 h from the onset of the blood infection, IL-10 tends to persist for longer during the septic state and performs as a valuable diagnostic biomarker." (PMID 38254697, 2024). "Upregulation of IL-1β and IL-6 mRNA expression was described in the cecum and ileum of broilers after in vivo infection with C. jejuni." (PMID 38907359, 2024). "Higher levels of IL-6 relative to the unstimulated control in peritoneal macrophages were also detected in response to RB51 infection or HKBA stimulation." (PMID 38464511, 2024). "We observed that in late presenters, IFN-ɣ, IL-6 and IL-10 levels were high and correlated with other markers of infection." (PMID 38992229, 2024). "Further studies have shown an early reduction in inflammatory recruitment at the site of infection, likely due to the drug’s effects on pro-inflammatory cytokines and chemokines, like IL-6, TNF, and MCP-1." (PMID 39204231, 2024). "Considerable inflammatory cells infiltrating in the endometrium, with high levels of pro-inflammatory cytokines of interleukin (IL)-6, IL-1β and tumor necrosis factor-α mRNA after infection." (PMID 39545261, 2024).
infection (continued). "IL-1β, TNF-α, and IL-6 are all upregulated in the context of inflammation and infection and are involved in the pathogenesis of preterm labor." (PMID 38791199, 2024). "At the strain level, all E. coli strains (with the exception of strain B at 2 h) induced significant levels of IL-6 over the course of the infection compared with the control (p < 0.00001)." (PMID 38672079, 2024). "MNKs have been implicated in mediating the production of pro-inflammatory cytokines, such as TNF-α, IL-6, and IL-1β, during infection and inflammation." (PMID 38980024, 2024). "Assessment of cytokines in the lung revealed that expression of Type 17 cytokines (Il-6, Cxcl1, Csf3) peaked at day 7 post-infection." (PMID 39338937, 2024). "While both IL‐6 inhibitors and corticosteroids effectively reduce toxicity, antimicrobial therapy should be instituted early when infection develops." (PMID 38923216, 2024). "Upregulating MCL-1 in neutrophils, IL-6 allows them to eliminate the pathogen, thereby preventing the efficient viral propagation, the consequent lung damage, and the fatal outcome of the infection." (PMID 38256213, 2024). "This panel analyzes, in the same serum sample, the inflammatory biomarkers procalcitonin, the inflammatory primary cytokine IL-6, and sCD14-ST, to provide a more comprehensive image of the inflammatory response to the infection." (PMID 39125464, 2024). "In studies with respiratory disease-challenged animals, production of IL-6 and IL-1β in blood after ex vivo stimulation decreases after infection when compared to the same assay before the disease challenge." (PMID 38764468, 2024). "For IL-6, infection induced an increase in this cytokine in all groups compared to the amount in the healthy control (p < 0.0043)." (PMID 39598539, 2024). "Subsequently, activated ATF3 then inhibits the transcription of the pro-inflammatory cytokine IL-6, thus promoting the progression of the infection." (PMID 38255898, 2024). "During natural infection with adenovirus, pro-inflammatory cytokines, such as IL-6 and TNF-alpha, are released." (PMID 39508450, 2024). "The 25–100 μL (0.5–2 MOI) RV16 infection significantly increased IL-6 protein production to similar levels (p < 0.001)." (PMID 39598462, 2024). "The excessive secretion of IL-6 and IL-10 indicates an early imbalance between pro- and anti-inflammatory res­ponses in patients with infection." (PMID 39212218, 2024). "IL-6−/− rodents (median survival: 7-days post infection [dpi]) showed significantly faster mortality than Wild-type- and IL-6−/− + rIL-6-treated mice (median survival: 8- and 9-dpi, respectively; P < 0.001)." (PMID 39334365, 2024). "Lung tissue sections from MHV68-infected K-RasLA1 mice at day 7 post-infection co-stained positively for both Ly6G and IL-6 (white arrows)." (PMID 39338937, 2024). "IL-6, which is classified as an acute-phase signalling molecule, controls and influences various immunological pathways in response to infection or tissue damage." (PMID 38892530, 2024). "It has been supported by a large number of research data that the serum concentration of IL-6 significantly increases in patients, especially those with severe symptoms, following infection with SARS-CoV-2." (PMID 38355623, 2024). "We observed significant increases in TNF-α, IL-1β, and IL-8 expressions and a clear synergistic increase in IL-6 expression with the P. gingivalis and F. nucleatum co-culture infection." (PMID 38612423, 2024). "Levels of pro-inflammatory cytokines IL-1β and IL-6 were reduced in the hypothermia group at 6 h post-infection." (PMID 38951957, 2024). "In contrast, a study of patients with esophageal variceal bleeding showed an association between the incidence of infection and death in these patients, and levels of high mobility protein group 1 (HMG1) and IL-6." (PMID 39273468, 2024).